HDHD5-AS1 (HDHD5 antisense RNA 1)
Synonyms: NCRNA00017; CECR4; CECR5-AS1
Gene: Long non-coding RNA gene on chromosome 22 (17,159,338 to 17,165,451, forward strand). Ensembl gene ENSG00000185837.
Diseases named in the same sentence as HDHD5-AS1 in open-access papers:
HDHD5-AS1 is named in the same sentence as 1 disease in open-access papers, as found by Europe PMC text mining. Sharing a sentence is not in itself a finding about the gene and the disease.
HDHD5-AS1 shares sentences with these, for which no sentence is quoted: cat-eye syndrome (1 paper).